IRGM (immunity related GTPase M)
Diseases named in the same sentence as IRGM in open-access papers (continued):
Sharing a sentence is not in itself a finding about the gene and the disease.
inflammatory bowel disease (14 papers, 2012 to 2024). A spectrum of small and large bowel inflammatory diseases of unknown etiology. "Other autophagy gene mutations (autophagy-related 16-like 1 (ATG16L1) and immunity-related GTPase family M protein (IRGM) that can predispose to inflammatory bowel disease (IBD) are also presented in the literature." (PMID 39000043, 2024). "One of the best-known targets of miRNA-regulated autophagy is the immunity-related GTPase family M protein (IRGM) clinically associated with inflammatory bowel disease." (PMID 30154791, 2018). "They overlap genes which have been associated with such disease; such as UGT2B17 (UDP Glucuronosyltransferase Family 2 Member B17) associated with the bone mineral density quantitative trait locus and IRGM (Immunity-related GTPase family M protein) associated with inflammatory bowel disease." (PMID 32272904, 2020). "Furthermore, genetic polymorphism of IRGM has been confirmed to be involved in the development of inflammatory bowel disease and in the induction of autophagy." (PMID 24626347, 2014). "To date, several polymorphisms in IRGM gene are reported to be linked with different diseases, especially autoimmune diseases such as inflammatory bowel disease (IBD) and SLE." (PMID 29992164, 2018). "Polymorphisms in immunity-related GTPase family M (IRGM) gene may be associated with inflammatory bowel disease (IBD) by affecting autophagy." (PMID 24232856, 2013). "Dysfuntion in autophagy genes such as ATG16L1, IRGM, and LRRK2, are emerging as potential susceptibility traits in patients with inflammatory bowel disease." (PMID 22363587, 2012). "In humans, polymorphisms in several autophagy-related genes, including IRGM, LRRK2, SMURF1 and ATG16L1, leading to autophagy deficiency are linked to inflammatory bowel disease (IBD) susceptibility." (PMID 28916785, 2017). "IRGM dysfunction is linked to inflammatory bowel disease (IBD), and while it is thought that defective intracellular killing of microbes underscores IBD susceptibility, studies have yet to address how IRGM/Irgm1 regulates immunity to microbes relevant to intestinal inflammation." (PMID 32453761, 2020). "Given the role of IRGM in inflammatory bowel disease (IBD) and Crohn’s, we utilized the dextran-sulfate (DSS)-induced colitis model to investigate the role of Irgm1 in Nlrp3 inflammasome activation." (PMID 30612879, 2019).
tuberculosis (13 papers, 2009 to 2023). A chronic, recurrent infection caused by the bacterium Mycobacterium tuberculosis. "Several studies establishing links between IRGM polymorphisms and other human inflammatory diseases have been conducted The most established associations have been with CD and tuberculosis." (PMID 35699756, 2022). "Other SNPs identified in the leprosy, tuberculosis and Crohn's-susceptibility studies have identified common genes including IRGM, LRRK2 and TNFSF15 suggesting that a theme of host microbial defence underlies the pathogenesis of these diseases." (PMID 20531959, 2010). "We have studied genetic variants of the human IRGM gene in a Ghanaian tuberculosis case-control group and found that the IRGM variant −261T provides relative protection against disease when the infection is caused by the Euro-American lineage of M. tuberculosis." (PMID 19750224, 2009). "While the association of the IRGM polymorphism that we found cannot unquestionably confirm the role of IRGM in tuberculosis, it adds evidence to the in vivo experiments in mice and human cells and supports the relevance of autophagy in the control of tuberculosis." (PMID 19750224, 2009). "In-vitro data strongly support a role for autophagy in control of M. tuberculosis, and a study involving 2010 patients with pulmonary TB and 2346 control subjects from Ghana has previously reported an association between a polymorphism in the autophagy gene IRGM and TB." (PMID 22879892, 2012). "To test whether IRGM plays a role in human infection, we studied IRGM gene variants in 2010 patients with pulmonary tuberculosis (TB) and 2346 unaffected controls." (PMID 19750224, 2009). "In addition, an association between IRGM (a human immunity-related GTPase) expression and the induction and execution of autophagy upon bacterial infections, such as tuberculosis, has been reported with regulation of autophagy formation in proportion to IRGM expression." (PMID 24626347, 2014).
Autoimmunity (11 papers, 2019 to 2025). The occurrence of an immune reaction against the organism's own cells or tissues. "Immunity related GTPase M (IRGM), an autoimmunity gene, contributes to regulating the interferon response by attenuating cGAS-STING and RIG-I-MAVS signaling." (PMID 36231136, 2022). "Recently, in a knockout mouse model, Irgm1 (the mouse orthologue of IRGM) was shown to control autoimmunity." (PMID 32715615, 2020). "The presence of IRGM/Irgm1 in humans and mice is shown to be largely protective against autoimmune disorders." (PMID 32715615, 2020).
colitis (6 papers, 2018 to 2022). Inflammation of the colon. "Since we found that IRGM negatively regulates RIPK2‐dependent pro‐inflammatory responses, we hypothesized that therapeutic inhibition of RIPK2 could reduce gut inflammation associated with Irgm1 depletion in shigellosis‐ and DSS‐induced colitis models." (PMID 36221902, 2022).
viral infection (6 papers, 2012 to 2021). "IRGM also has been confirmed to be associated to mitochondria and interact with autophagy-associated proteins (ATG5) directly upon virus infection." (PMID 25853521, 2015). "It remains however possible that cytosolic isoforms of IRGM contributes to autophagy induction upon viral infection." (PMID 23335927, 2012). "In this study, we show that IRGM expression is increased upon viral infection." (PMID 34467632, 2021). "Here, we discuss how IRGM might contribute to human autophagy upon viral infection, and why its targeting might be beneficial to virus replication." (PMID 23335927, 2012). "As discussed here, IRGM could be a key protein for autophagy manipulation upon viral infection." (PMID 23335927, 2012). "Since the protein level of IRGM is not influenced by the HCV infection, this indicates that the reduced fraction of IRGM colocalizing with ASC results from the viral infection and is not a consequence of reduced levels of IRGM protein." (PMID 33208442, 2021). "IRGM negatively regulates IFN responses and IRGM expression is increased upon viral infection." (PMID 34467632, 2021).
autoimmune disease (5 papers, 2019 to 2024). A disorder resulting from loss of function or tissue destruction of an organ or multiple organs, arising from humoral or cellular immune responses of the individual to their own tissue constituents. "Loss of function of IRGM has been linked to the pathogenesis of several autoimmune diseases." (PMID 32715615, 2020). "Loss of function of Immunity Related GTPase M (IRGM) has also been associated to several autoimmune diseases, but its mechanism of action is unknown." (PMID 32715615, 2020). "Taken together, this study defines the molecular mechanisms by which IRGM maintains interferon homeostasis and protects from autoimmune diseases." (PMID 32715615, 2020). "Given the linkage of IRGM with so many inflammatory and autoimmune disorders, it is surprising that IRGM’s mechanism of action in regulating inflammation remains unclear." (PMID 30612879, 2019). "Nevertheless, this study defines the mechanism by which IRGM is a master regulator of IFN responses and highlights IRGM as a strong potential target for new therapeutic interventions against inflammatory/autoimmune diseases." (PMID 32715615, 2020).
leprosy (5 papers, 2010 to 2026). Leprosy is a chronic infectious disease affecting primarily the skin and peripheral nervous system. "Studies showed that IRGM polymorphism was associated with the increased susceptibility to leprosy by affecting inflammatory cytokines, with T-lep patients showing the highest expression, whereas L-lep had the lowest expression of IRGM." (PMID 38133338, 2023). "The IRGM gene, which regulates autophagy, has also been confirmed to be associated with leprosy susceptibility; it was demonstrated that only rs13361189 TC and CC genotypes are significantly associated with leprosy." (PMID 38440733, 2024).
pulmonary tuberculosis (5 papers, 2009 to 2013). A bacterial infection that affects the lungs and is caused by Mycobacterium tuberculosis. "In the present study, we examined the impact of IRGM −1208 A/G, −1161 C/T, and −947 C/T polymorphisms on pulmonary tuberculosis (PTB) risk in a sample of Iranian population." (PMID 23049477, 2012). "In addition, variants of the immunity-related GTPase M (IRGM) were associated with protection from pulmonary tuberculosis due to Euro-American strains of M. tuberculosis." (PMID 21060820, 2010).
glioma (4 papers, 2020 to 2025). A benign or malignant brain and spinal cord tumor that arises from glial cells (astrocytes, oligodendrocytes, ependymal cells). "In human glioma cell lines, overexpression of IRGM was linked to increased cell colony formation, cell proliferation, and Akt activation." (PMID 35699756, 2022). "IRGM polymorphisms have been investigated in relation to cancer including gastric cancer, renal cell carcinoma, and glioma." (PMID 35699756, 2022). "Previous studies show gliomas contain a plenty of macrophages, and tumor-associated macrophages correlate with progression and angiogenesis of gliomas by several ways, including: microRNA-macrophage feedback loop, extracellular lipid loading and cytokines like OPN, IRGM, IL-6." (PMID 32509446, 2020).
Sepsis (4 papers, 2014 to 2026). Sepsis is defined as life-threatening organ dysfunction caused by a dysregulated host response to infection. "Polymorphism of autophagy-related genes (ATG16L1 and IRGM) was associated with severity and mortality of sepsis." (PMID 25625512, 2015). "The present study suggests the possibility that TT homozygosity at the IRGM(+313) locus may be involved in the suppression of IRGM expression in severe sepsis, thereby suppressing autophagy and leading to a poor clinical outcome." (PMID 24626347, 2014).
atherosclerosis (3 papers, 2017 to 2025). A disease characterized by the build-up of fatty material and calcium deposition in the arterial wall resulting in partial or complete occlusion of the arterial lumen. "However, it remains unknown whether IRGM/Irgm1 affects macrophage survival and plaque stability during atherosclerosis." (PMID 34646375, 2021). "In our previous studies, we found that IRGM/Irgm1 promotes ox-LDL uptake by macrophages 20, as well as macrophage polarization to the pro-inflammatory M1 phenotype 21 during the initial phase of atherosclerosis." (PMID 34646375, 2021).
Sjogren syndrome (3 papers, 2020 to 2024). An autoimmune disorder in which immune cells attack and destroy the glands that produce tears and saliva. "Irgm1−/− mice display susceptibility to intestinal inflammation in multiple contexts (42, –, 44), increased cytokine production upon LPS treatment, and type I interferonopathy resembling Sjogren’s syndrome, paralleling several human disease syndromes associated with IRGM variants." (PMID 38501887, 2024).
autoimmune thyroid disease (2 papers, 2018 to 2020). Inflammatory disease of the thyroid gland due to autoimmune responses leading to lymphocytic infiltration of the gland. "The present study aimed to examine the roles of IRGM polymorphisms in autoimmune thyroid diseases (AITD)." (PMID 29992164, 2018).
gastric cancer (2 papers, 2018 to 2022). A primary or metastatic malignant neoplasm involving the stomach. "H. pylori-infected patients harbouring IRGM rs13361189 demonstrated a remarkably increased risk of gastric cancer development." (PMID 35699756, 2022). "Besides, a recent study suggested IRGM polymorphisms were related to gastric cancer in Chinese." (PMID 29992164, 2018). "In gastric cancer, mRNA and protein levels of IRGM were shown to be significantly upregulated in the peripheral blood of cancer patients compared to healthy controls, and these levels were higher in stage IV than in stage I cancer patients." (PMID 35699756, 2022).
hepatocellular carcinoma (2 papers, 2011 to 2022). A malignant tumor that arises from hepatocytes. "In hepatocellular carcinoma (HCC), overexpression of the metallocarboxypeptidase AGBL2, an independent prognostic biomarker that promotes HCC cell survival and proliferation, enhanced autophagy and inhibited apoptosis via IRGM up-regulation." (PMID 35699756, 2022).
HIV-1 infection (2 papers, 2021 to 2025). The type species of lentivirus and the etiologic agent of acquired immunodeficiency syndrome (AIDS). "Further studies are warranted to investigate TFEB localization and phosphorylation status, as well as the expression and activity of IRGM and GABARAP proteins, in the context of vitamin D3 supplementation during HIV-1 infection." (PMID 40514685, 2025).
systemic lupus erythematosus (2 papers, 2018 to 2020). An autoimmune multi-organ disease typically associated with vasculopathy and autoantibody production. "Moreover, polymorphisms in IRGM and ATG5 polymorphisms, and variations in PRDM1-ATG5 intergenic region have been associated with systemic lupus erythematosus (SLE)." (PMID 30127786, 2018).
Chlamydia infection (1 paper, 2024). "There is no known role for human IRGM in Chlamydia infection, and because of the vastly divergent mechanisms of cell-autonomous immunity between mice and humans, it is exceedingly unlikely that human IRGM regulates protective immunity to C. trachomatis, as supported by some experimental evidence." (PMID 38501887, 2024).
glioblastoma (1 paper, 2025). The most malignant astrocytic tumor (WHO grade IV). "According to the literature, among the genes whose expressions change after treatment and have an LTR12C element at the TSS site, only IRGM, GBP2, GBP5, and TP63 are known to play a meaningful role in glioblastoma." (PMID 40498028, 2025).
Hashimoto thyroiditis (1 paper, 2018). An autoimmune disorder caused by the production of autoantibodies against thyroid tissue. "Three polymorphisms in IRGM gene (rs10065172, rs4958847, and rs13361189) were genotyped in 1569 participants (488 with Graves' disease, 292 with Hashimoto's thyroiditis, and 789 healthy controls) using PCR-based ligase detection reaction method." (PMID 29992164, 2018).
intestinal inflammation (1 paper, 2017). "Conversely, other autophagy-related genes (ATG16L1 and IRGM) seemed to play important roles for autophagy in maintaining intestinal homeostasis, and the overall dysfunction of autophagy resulted in being a major risk factor for the onset of chronic intestinal inflammation." (PMID 28208686, 2017).
liver cancer (1 paper, 2021). An epithelial or non-epithelial malignant neoplasm that arises from the liver. "It has been reported that IRGM plays an important role in non-small cell lung cancer and liver cancer by regulating autophagy." (PMID 35280928, 2021).
lung adenocarcinoma (1 paper, 2016). A carcinoma that arises from the lung and is characterized by the presence of malignant glandular epithelial cells. "In addition to JAK1/2-STAT1-IRF-1 signaling, the immunity-related GTPase family M protein (IRGM) mediates IFN-γ-induced autophagy and autophagy-mediated mimic extracellular trap cell death (ETosis) in A549 human lung adenocarcinoma cells." (PMID 27575372, 2016).
multiple sclerosis (1 paper, 2016). A progressive autoimmune disorder affecting the central nervous system resulting in demyelination. "Similar to CD, IRGM has also been implicated in multiple sclerosis based on the observation that IRGM expression is strongly induced in affected lesions of multiple sclerosis patients." (PMID 26222012, 2016).
Mycobacterium infection (1 paper, 2011). Infections with bacteria of the genus Mycobacterium. "Several key molecules for this process have been identified, including murine Irgm1 (LRG-47) guanosine triphosphate and its human orthologue IRGM, which is important for controlling Mycobacterium infections." (PMID 21760796, 2011).
Pancytopenia (1 paper, 2018). An abnormal reduction in numbers of all blood cell types (red blood cells, white blood cells, and platelets). "Regarding HSPCs, genetic deletion of Irgm1, for which IRGM is a human ortholog, results in pancytopenia due to inadequate cell expansion when challenged with mycobacterium or T. cruzi." (PMID 30405604, 2018).
sarcoidosis (1 paper, 2016). Sarcoidosis is a multisystemic disorder of unknown cause characterized by the formation of immune granulomas in involved organs. "We genotyped 201 patients and 1023 healthy controls for risk variants in NOD2, IRGM, IL23R, ATG16L1 (CD), BTNL2 (sarcoidosis), and FLG (atopy)." (PMID 27306066, 2016). "We therefore tested genetic variants known to be strongly associated with an increased risk of CD (NOD2, IRGM, IL23R, and ATG16L1), sarcoidosis (BTNL2), and atopy (FLG) for association with OFG." (PMID 27306066, 2016). "DNA samples from 201 patients (111 OFG only and 90 OFG+CD) were genotyped for variants known to be strongly associated with an increased risk of CD (NOD2, IRGM, IL23R, and ATG16L1), sarcoidosis (BTNL2), and atopy (FLG)." (PMID 27306066, 2016).
steatosis (1 paper, 2021). Increased lipid within the cytoplasm of cells. "For instance, the rs10065172 variant in the autophagy-related IRGM gene may increase the risk of developing steatosis and IRGM knockdown inhibits autophagic flux and increases LD content in HepG2 cells." (PMID 34680476, 2021).
type 1 interferonopathy (1 paper, 2022). Conditions in which increased type 1 interferon signaling leads to autoimmune and neurological disorders. "Thus, by modulating mitochondrial fission and polyubiquitination of PRRs, IRGM prevents type-1 interferonopathy." (PMID 35699756, 2022).